CLCN1 (chloride voltage-gated channel 1)
Description:
Voltage-gated chloride channel involved in skeletal muscle excitability. Generates most of the plasma membrane chloride conductance in skeletal muscle fibers, stabilizes the resting membrane potential and contributes to the repolarization phase during action potential firing. Forms a homodimeric channel where each subunit has its own ion conduction pathway. Conducts double-barreled currents controlled by two types of gates, two fast glutamate gates that control each subunit independently and a slow common gate that opens and shuts off both subunits simultaneously. Has a significant open probability at muscle resting potential and is further activated upon membrane depolarization. Permeable to small monovalent anions with ion selectivity for chloride > thiocyanate > bromide > nitrate > iodide.
Synonyms: ClC-1; CLC1
Tractability: Small molecule: it belongs to a druggable protein family. Antibody: UniProt places it where antibodies can reach, with high confidence; its Gene Ontology location is reachable by antibodies, with high confidence; UniProt predicts a signal peptide or a membrane-spanning region.
Gene: Protein-coding gene on chromosome 7 (143,316,111 to 143,352,083, forward strand). Ensembl gene ENSG00000188037.
Subcellular location: Cell membrane; Cell membrane, sarcolemma; Cell membrane, sarcolemma, T-tubule
Pathways (Reactome):
Transport of small molecules: Stimuli-sensing channels
Gene Ontology:
Molecular function: protein binding; protein homodimerization activity; voltage-gated chloride channel activity; chloride channel activity; chloride transmembrane transporter activity
Biological process: chloride transmembrane transport; muscle contraction; chloride transport; transmembrane transport
Cellular component: plasma membrane; membrane; sarcolemma; T-tubule
Genetic constraint (gnomAD): Loss-of-function variants: 94 observed, 108.74 expected, observed/expected ratio (o/e) 0.86, 90% interval 0.73 to 1.03. The upper end of that interval is the gene's LOEUF score, 1.03, which puts it in group 4 of 6, group 1 being the genes least tolerant of losing a copy. Missense variants: 1,176 observed, 1,270.1 expected, observed/expected ratio (o/e) 0.93, 90% interval 0.88 to 0.97. Synonymous variants: 482 observed, 488.03 expected, observed/expected ratio (o/e) 0.99, 90% interval 0.92 to 1.07.
Homologues: Orthologues: chimpanzee CLCN1 (98% identical), macaque CLCN1 (98% identical), guinea pig CLCN1 (89% identical), pig CLCN1 (89% identical), dog CLCN1 (89% identical), rat Clcn1 (88% identical), mouse Clcn1 (88% identical), rabbit CLCN1 (86% identical), zebrafish clcn1a (57% identical), zebrafish clcn1b (55% identical), tropical clawed frog clcn1 (55% identical), Drosophila melanogaster ClC-c (19% identical), and 1 more. Paralogues in human: CLCN2 (47% identical), CLCNKB (29% identical), CLCNKA (28% identical), CLCN5 (20% identical), CLCN4 (19% identical), CLCN3 (19% identical), CLCN7 (18% identical), CLCN6 (17% identical).
Diseases named in the same sentence as CLCN1 in open-access papers:
CLCN1 is named in the same sentence as 76 diseases in open-access papers, as found by Europe PMC text mining. Sharing a sentence is not in itself a finding about the gene and the disease. The quoted sentences say what the papers report.
Myotonia (104 papers, 2008 to 2026). An involuntary and painless delay in the relaxation of skeletal muscle following contraction or electrical stimulation. "In muscle channelopathy, CLCN1 variants were identified in 2 of 3 patients presenting with typical myotonia and muscle hypertrophy." (PMID 40494860, 2025). "While it’s clear that missplicing or loss of function of Clcn1 directly causes myotonia, there appear to be molecular modifiers that allow certain muscles to avoid myotonia and children with CDM to avoid the early onset of the symptom." (PMID 40811031, 2025). "Myotonia is linked to aberrant alternative splicing of the muscle-specific CLCN1 gene, resulting in reduced chloride ion conductance across muscle membranes." (PMID 40938889, 2025). "The mutations of the CLCN1 gene result in a decrease in channel opening probability and make the membrane excitable, manifesting myotonia." (PMID 40535402, 2025). "Most previously reported cases of CLCN1-associated myotonia in dogs presented with stiffness that improved with activity and variable muscle hypertrophy." (PMID 38473107, 2024). "Mbnl1KO mice display several muscle abnormalities, including overt myotonia beginning at approximately 6 weeks of age that is caused by abnormal AS of Clcn1 mRNA, an increase in mislocalized nuclei, and splitting of myofibers." (PMID 39258536, 2024). "Defects in skeletal muscle chloride conductance due to mis‐splicing of CLCN1 are postulated to be causative of myotonia and restoration of aberrant exon 7a inclusion corrects this phenotype in DM1 mouse models." (PMID 39450929, 2024). "While myotonia caused by mutations in CLCN1 has been well-documented in purebred dogs, reports and genetic investigations in mixed-breed dogs remain limited but have been described." (PMID 39559538, 2024). "Mutations in the CLCN1 gene responsible for hereditary myotonia have been documented in various dog breeds, including Miniature Schnauzers, Australian Cattle Dogs, Labrador Retrievers, American Bulldogs." (PMID 39559538, 2024). "In myotonic dystrophy type 1 (DM1), deregulated alternative splicing of the muscle chloride channel Clcn1 causes myotonia, a delayed relaxation of muscles due to repetitive action potentials." (PMID 37029100, 2023). "Several CLCN1 variants with strong genetic evidence of causal implication in myotonia have been reported to behave very similarly to WT channels in in vitro electrophysiological studies." (PMID 37892996, 2023). "Although the pathogenesis of MC is not yet fully understood, it is well known that mutations in CLCN1 produce a reduction in the chloride conductance that leads to membrane hyperexcitability, triggering myotonia." (PMID 37892996, 2023). "The adr/adr mouse presents severe myotonia due to a missense mutation in the skeletal muscle chloride channel gene CLCN1." (PMID 36614292, 2023). "Loss-of-function mutations in the skeletal muscle chloride channel ClC-1 (encoded by the CLCN1 gene), cause another form of hereditary myotonia, namely myotonia congenita." (PMID 36614292, 2023). "ATP2A1 exon 22 exclusion is associated with muscle dysfunction, CLCN1 exon 7a inclusion is associated with myotonia, and MBNL1 exon 5 inclusion is associated with MBNL1 subcellular localization." (PMID 37111604, 2023). "Mutations in distinct myotonia-associated genes (CLCN1, SCN4A, DMPK, CNBP) can co-occur in a patient and modify the presentation compared to a patient carrying a single gene mutation." (PMID 34529042, 2022). "In particular, in the HSALR model recovery of the alternative splicing of the muscle chloride-channel (Clcn1) transcript, which is involved in myotonia, was associated to a marked reduction in the defect." (PMID 35563013, 2022). "NDMs are a group of hereditary skeletal muscle ion channelopathies characterized by myotonia and caused by CLCN1 or SCN4A variants, including MC, PMC, and SCM." (PMID 35350395, 2022).
Myotonia (continued). "In conclusion, NDMs are a group of hereditary skeletal muscle ion channelopathies characterized by myotonia and caused by CLCN1 or SCN4A variants, mainly including MC and PMC." (PMID 35350395, 2022). "CLCN1 contributes to membrane repolarization in skeletal muscle cells after muscle contraction, and its mutation was known to cause myotonia." (PMID 36675693, 2022). "Our study reported five Chinese patients with CLCN1-related myotonia, which revealed two novel likely pathogenic variants: c.962T>A (p.V321E) and c.1250A>T (p.E417V), which expanded the clinical and genetic spectrum of MC patients in the Chinese population." (PMID 34790634, 2021). "The pathophysiological mechanism of myotonia is mainly related to reduced activity of the chloride channels and consequently reduced chloride conductivity in CLCN1, whereas in SCN4A-myotonias it is caused by an impaired inactivation of the NaV1.4 channels." (PMID 33263785, 2021). "Today, it is known that different types of Clcn1 mutations are responsible for dominant and recessive myotonia." (PMID 32499703, 2020). "A previous study showed that 2-fold upregulation of MBNL1 protein by transduction of a recombinant adeno-associated viral vector reversed missplicing of Clcn1, Ldb3, Serca1, and Tnnt3, resulting in a significant reduction in myotonia in a DM1 mouse model." (PMID 32054946, 2020). "Most pathogenic CLCN1 mutations cause loss-of-function phenotypes in the CLC-1 channel and thus increase membrane excitability in skeletal muscle cells, consequently manifesting myotonia." (PMID 32407401, 2020). "Loss-of-function mutations of the chloride channel ClC-1 encoded by CLCN1, causing hyperexcitability in the skeletal muscle are commonly found in patients with myotonia, an impairment of muscle relaxation." (PMID 32466254, 2020). "Myotonia can be caused by mutations in CLCN1 that reduce the function of the skeletal muscle chloride channel ClC-1 (myotonia congenita, MC)." (PMID 31772215, 2019). "For these mutations, a powerful experimental approach would be the generation and analysis of knock-in mice carrying the myotonia-related CLCN1 mutations, since myotonic mice are an established model for chloride channel myotonia." (PMID 32010054, 2019). "For example, deregulated splicing of the CLCN1 causes reduced permeability for chloride ions in the sarcolemma, contributing to myotonia—delayed relaxation after voluntary muscle contraction, and a core symptom of DM." (PMID 30794581, 2019). "The patient carries a concomitant synonymous CLCN1 variant that likely worsens the myotonia and potentially contributes to the amelioration of muscle paralysis." (PMID 31772215, 2019). "Instead, enhanced myotonia was the result of the synergy between Clcn1 missplicing caused by Mbnl1 deletion alone, and defective CLCN1 translation, caused by combined inactivation of MBNL1 and MBNL3 proteins." (PMID 30050493, 2018). "The specific mutation in the CLCN1 gene in our patient has been previously reported in individuals with Becker’s type or recessive generalized myotonia." (PMID 27266866, 2016). "Among them, abnormal alternative splicing of Clcn1 results in a loss-of-function of the membrane-associated chloride channels and causes myotonia, which is one of the major symptoms of DM1." (PMID 27126921, 2016). "The myotonia is likely to be caused by a hyperexcitability of muscles due to the loss of CLCN1 function." (PMID 26965373, 2016). "Myotonia congenita (MC) is an inherited myotonia due to mutations in the CLCN1 gene encoding the skeletal muscle ClC-1 chloride channel." (PMID 26007199, 2015). "Down-regulation of the CLCN1 gene, which encodes the major voltage-gated chloride channel that controls the membrane excitability of skeletal muscle, causes the myotonia that is characteristic of DM." (PMID 25883322, 2015).
Myotonia (continued). "In summary, we evaluated the functional consequences of four myotonia-associated CLCN1 mutations that predict single amino acid substitutions in the amino-terminus of hClC-1." (PMID 26502825, 2015). "A plethora of mutations in the CLCN1 gene are known to produce dominant and recessive myotonia in humans and other animals." (PMID 25964741, 2015). "In a systematic screen of all 23 exons of the CLCN1 gene in seven patients with recessive generalized myotonia (Becker) we found four missense mutations predicting amino acid exchanges Q43R, S70L, Y137D and Q160H." (PMID 26502825, 2015). "Studies in mice, dogs, humans and goats confirmed myotonia associated with functional defects in chloride channels and mutations in a skeletal muscle chloride channel (CLCN1)." (PMID 25356766, 2014). "In this study, we generated zebrafish models for myotonia congenita by expressing human CLCN1 (hCLCN1) carrying mutations associated with human patients suffering from myotonia under the control of the muscle specific promoter of the α-actin gene." (PMID 25083883, 2014). "CLCN1 mutations impair CLCN1 functions and render the plasma membrane hyper-excitable, leading to clinical myotonia and typical electromyographic changes." (PMID 25083883, 2014). "Sequence analysis of CLCN1 showed that mutations linked to myotonia are scattered over the entire sequence of the channel protein, and include insertion/deletions, missense, nonsense, and splicing mutations." (PMID 25083883, 2014). "DM-associated myotonia is caused by mis-regulated splicing of Clcn1 pre-mRNA and depletion of full-length CLCN1 protein from the sarcolemma." (PMID 24293317, 2013). "Myotonia exists in both autosomal recessive (Becker's disease) and dominant forms (Thomsen's disease), and is caused by mutations in the CLCN1 gene." (PMID 22253609, 2012). "Mutations in CLCN1 have been associated with myotonia in Miniature Schnauzer and the Australian Cattle Dog." (PMID 22253609, 2012). "Over the past decades since the implication of ClC-1 deficiency as the cause of myotonia in DM1, it has been shown that numerous splice events in Clcn1 transcript, in addition to E7a, were upregulated in DM1 patients and disease models, including intron 2 retention." (PMID 41000779, 2025). "This in turn produces a complex array of clinical findings in which specific endophenotypes, such as myotonia, heart block, or insulin resistance, are linked to splicing defects of particular genes, such as CLCN1 (chloride channel), SCN5A (sodium channel), or INSR (insulin receptor)." (PMID 38165038, 2024). "The only other reported case of ovine myotonia segregated with a variant in CLCN1." (PMID 39765607, 2024). "The mis-splicing of and reduction in Clcn1 are associated with the development of myotonia in DM1." (PMID 37445828, 2023). "However, 6aKC-PMOs had a slightly superior effect on myotonia, perhaps because of their superior action correcting its cause: the abnormal splicing on Clcn1 transcripts." (PMID 37744174, 2023). "Finally, our data suggest that it must be stressed that genetic testing in myotonia patients should include both CLCN1 and SCN4A genes, even if a mutation has been found in one of them." (PMID 33670307, 2021). "The SCN4A associated myotonia commonly involves the facial muscles with eyelid myotonia; the muscle weakness can occur more frequently and may persist longer than in CLCN1 patients." (PMID 33263785, 2021). "Main dysfunction types of the CLCN1 gene associated with myotonia congenital." (PMID 32407401, 2020). "Latent myotonia was detected by needle EMG in p.R1460Q carriers, and some had symptomatic myotonia, especially with the coincident occurrence of an independently segregating mutation of the chloride channel gene CLCN1 (p.R894X associated with recessive myotonia congenita)." (PMID 30824560, 2019). "Thus, it should be considered as first line therapy for patients with concomitant SCN4A and CLCN1 mutations associated with myotonia." (PMID 31772215, 2019).
Myotonia (continued). "Few patients may, however, display a severe myotonia and in some of these cases additional mutations in ion channel genes CLCN1 and SCN4A have been identified." (PMID 29770119, 2018). "However, an association between DM2 patients with prominent myotonia and mutations on CLCN1 or SCN4A, encoding for the α subunit of the skeletal muscle sodium channel Nav1.4, have been found." (PMID 30038349, 2018). "Here, we describe a recessive form of hereditary myotonia in a mixed-breed dog including the clinical presentation, electrophysiological abnormalities, and genetic characterization of a novel complex exon 15 mutation of the CLCN1 gene, along with the genetic investigation of its relatives." (PMID 39559538, 2024). "It should be mentioned, however, that it can enhance the myotonia in DM patients as even heterozygous carriers of CLCN1 variants can present with subclinical myotonia that is most probably combined with the expansion mediated alternative splicing disturbance of CLCN1 in DM patients." (PMID 34501382, 2021). "Mis-splicing of select MBNL-dependent events have been linked to disease symptoms, including insulin resistance (INSR), myotonia (CLCN1), and cardiac arrhythmia (SCN5A) in DM1 cell and mouse models." (PMID 39836447, 2025). "Myotonia congenita (MC), a rare inherited disease, is caused by variations in the skeletal muscle chloride voltage-gated channel one gene (CLCN1) and is characterized by symptoms of myotonia and muscle hypertrophy." (PMID 40535402, 2025). "Numerous transcripts are mis‐spliced, although only a select few have been linked to disease phenotypes in DM1 cell and animal models, including CLCN1 and myotonia,21, 22SCN5A and cardiac arrhythmia, and BIN1 and muscle weakness." (PMID 39450929, 2024). "The expression of chloride channel 1 (Clcn1), the key trigger of myotonia in DM1, was also corrected by TG." (PMID 37445828, 2023). "The improvement in fiber diameter and reduction of muscle injury in ASO-treated mice indicate a therapeutic benefit of myotonia reduction and supports further development of Clcn1-targeted therapies for DM1." (PMID 37029100, 2023). "Here, we describe a patient with chronic proximal myopathy, subtle clinical myotonia and electrical myotonia on electromyography (EMG) related to both pathogenic variants on PNPLA2 and CLCN1 genes." (PMID 37106355, 2023). "Remarkably, the list of TG-corrected genes involved in the regulation of transport includes chloride ion channel 1 (Clcn1), associated with the development of the main muscle symptom of DM1, myotonia." (PMID 37445828, 2023). "For example, CLCN1 and INSR mis-splicing are responsible for myotonia and insulin resistance, respectively, while SCN5A is linked to heart conduction defects and cardiac arrhythmias." (PMID 37111604, 2023). "Myotonia alleviation depends on the expression of the correct Clcn1 channel isoform, followed by the accumulation of CLCN1 proteins in the membrane of muscle fibers." (PMID 37744174, 2023). "Our results demonstrate that fiber type transitions in DM1 result from myotonia and are reversible, and support the development of Clcn1-targeting therapies for DM1." (PMID 37029100, 2023). "Co-existing mutations in CLCN1 and SCN4A seem to enhance the myotonia and/or muscle pain in DM2 patients." (PMID 35205411, 2022). "We enrolled 70 patients (64 families): 48 (68.5%) patients had a diagnosis of CLCN1-myotonia and 22 (31.4%) of SCN4A-myotonia." (PMID 33263785, 2021). "In mice, a spontaneous Clcn1 mutant line (Clcn1adr) was described with myotonia, muscle weakness, reduced growth and brittle bones." (PMID 34142127, 2021). "This study demonstrates that CLCN1-p.W322* and SCN4A-p.R1463H mutations can act alone or in combination as inducers of myotonia." (PMID 33670307, 2021). "CLCN1-myotonias, also known as myotonia congenita (MC), are to be distinguished into the autosomal dominant type Thomsen (TMC) and the autosomal recessive type Becker (BMC), related to the type of mutation." (PMID 33263785, 2021).